RNASET2 (ribonuclease T2)
Diseases named in the same sentence as RNASET2 in open-access papers (continued):
Sharing a sentence is not in itself a finding about the gene and the disease.
renal cell carcinoma (1 paper, 2023). "Finally, the high expression of RNASET2 was verified using the renal cell carcinoma cell lines (A498, 786-O and OSRC-2) and HK-2, as well as 8 pairs of ccRCC tissues and adjacent normal tissues from our medical center." (PMID 37679715, 2023).
skin cancer (1 paper, 2024). "PTGES2, RNASET2, SF3B4, and STX8 showed significant associations with skin cancer after FDR correction." (PMID 39035989, 2024). "Interestingly, PTGES2, RNASET2, SF3B4, and STX8, associated with skin cancer risk, were also significantly associated with NMSC and BCC risks." (PMID 39035989, 2024). "Furthermore, prostaglandin E synthase 2 (PTGES2), ribonuclease T2 (RNASET2), SF3B4, and STX8 were significantly associated with skin cancer risk after FDR correction for multiple testing (FDR <0.05)." (PMID 39035989, 2024). "In the replication test of ICD10 classified skin cancer subtypes, SNPs rs11575078 and rs2247315 emerged as top SNPs for analyzing colocalizaton between RNASET2 and non-epithelial skin cancer types in both UKB-PPP and deCODE studies." (PMID 39035989, 2024).
Stroke (1 paper, 2025). Sudden impairment of blood flow to a part of the brain due to occlusion or rupture of an artery to the brain. "We identified 179 significant SNPs and five common risk genes for RA and stroke (IRF5, RNASET2, ZNF438, UBE2LS, and SYNGR1)." (PMID 39953635, 2025).
synovitis (1 paper, 2024). Inflammation of a synovial membrane. "Given the close proximity of PMN and macrophages found in inflamed joint we can speculate that the RNASET2 release potentiated by PMN NETosis contributes to the recruitment of macrophages and that RNASET2 is involved in the active phase of synovitis since the early stages of disease." (PMID 39500942, 2024).
thyroid cancer (1 paper, 2021). "Among them, there were 7 mutation sites of importance for HT-related genes [CTLA4 (1 site), BACH2 (3 sites), and RNASET2 (3 sites)] where at least two patients with thyroid cancer experienced mutations." (PMID 34993154, 2021). "Our research group used bioinformatics to analyze the Oncomine database and found that HT-related genes (TSHR, BACH2, RNASET2, CTLA4, PTPN22, IL2RA) were expressed in different types of thyroid cancer." (PMID 34993154, 2021). "Among them, TSHR and RNASET2 were highly expressed in malignant tumors, especially TSHR in thyroid cancer, while BACH2, CTLA4, PTPN22, IL2RA, and other immune-related genes are expressed significantly lower in thyroid cancer." (PMID 34993154, 2021).
tumor (28 papers, 2011 to 2026). "This response was associated with long-term tumor rejection, underscoring RNASET2’s capacity to orchestrate effective antitumor immunity." (PMID 40389981, 2025). "The absence of this phenotype in PC-3 cells likely underlie their resistance to RNASET2-mediated tumor suppression." (PMID 40389981, 2025). "RNASET2, a member of the T2 family of extracellular ribonucleases, has been associated with anti-tumor activities." (PMID 38576019, 2024). "RNASET2 has been associated with anti-tumor activities, since its overexpression is a good prognostic index in several neoplastic diseases." (PMID 34299186, 2021). "In fact, RNASET2 has been recently associated with immune cell functions, highlighting its potential involvement in innate and, so far, anti-tumor immunity." (PMID 34299186, 2021). "So far, these evidences strongly indicate that RNASET2 expression in both EOC cells is associated with a less aggressive tumor phenotype in terms of proliferation, with inhibition of ECM-dependent src kinase activation." (PMID 30813308, 2019). "Human RNASET2 is a glycoprotein encoded by the RNASET2 gene which is located on chromosome 6 (6q27) and demonstrated to be a tumor suppressor gene." (PMID 25815360, 2015). "Human RNASET2 is a T2-RNase glycoprotein encoded by RNASET2, a recognized tumor suppressor gene located on chromosome 6 (6q27)." (PMID 25426551, 2014). "RNASET2 overexpression also promoted the release of soluble factors related to monocyte/macrophage recruitment/activation and cytokines/chemokines, linked to immune cell-mediated anti-tumor responses." (PMID 40389981, 2025). "In EOC biopsies (n = 101), analyzed by immunohistochemistry, RNASET2 was found heterogeneously expressed among tumors with different clinical–pathological characteristics and, in some cases, its expression localized to tumor-associated ECM." (PMID 30813308, 2019). "We show here that RNASET2 staining could be also detected in tumor-associated ECM, pointing at the tumor cell–ECM interaction as a plausible novel biological process involved in RNASET2-mediated tumor suppression." (PMID 30813308, 2019). "Strikingly, RNASET2 exerts its ‘antitumor function’ independently from its ribonuclease activity and we have demonstrated that its expression in tumor cells in vivo is associated with the recruitment into the tumor mass of cells from the monocyte/macrophage lineage committed to anticancer activity." (PMID 30813308, 2019). "Moreover, since RELB is directly involved in the NK-κB pathway, it is tempting to postulate a role for RNASET2 in RELB-mediated control of tumor-associated macrophages (TAM) polarization." (PMID 21646684, 2011). "In addition, RNASET2 protein can be found accumulated in the cytoplasm or in tumor-associated ECM." (PMID 30813308, 2019). "This highlights a potentially conserved mechanism by which RNASET2 modulates the tumor microenvironment across different cancer models." (PMID 40389981, 2025). "Taken together, our results reinforce the pleiotropic role of RNASET2 in mediating both cell-autonomous and immune-mediated tumor suppression." (PMID 40389981, 2025). "We next investigated the contribution of RNASET2 expression on the modulation of key features of the metastatic behavior in PCa tumor cells, specifically cell adhesion and migration." (PMID 40389981, 2025). "The in vivo oncosuppressive activity of RNASET2 involves the establishment of a crosstalk between RNASET2-expressing cancer cells and components of the tumor microenvironment (TME) belonging to the innate immune system (mostly tissue macrophages)." (PMID 40389981, 2025). "We first assessed the expression of RNASET2 in tumor tissues versus matched adjacent non‐tumor tissues in HCC patients and N‐nitrosodiethylamine (DEN)‐induced mouse HCC model using Western blot (WB) and immunohistochemistry (IHC) staining." (PMID 39903758, 2025).
tumor (continued). "We observed that these two cancer cell lines showed a marked difference in their response to RNASET2 overexpression, likely modulated by intrinsic cellular features and tumor stage in PCa context." (PMID 40389981, 2025). "To assess the clinical relevance of RNASET2 in patients with HCC, we analyzed RNASET2 levels in both adjacent non‐tumor tissues and tumor tissues of HCC patients using the GSE76427 database." (PMID 39903758, 2025). "Considering the importance of the Warburg effect in the malignancy progression of tumor, we assessed the effect of RNASET2 on glycolysis in HCC." (PMID 39903758, 2025). "For tumor biology, RNASET2 is a multifunctional protein, which has dual‐directional roles in tumor development." (PMID 36728187, 2023). "The results revealed that the RNASET2 protein expression level significantly correlated with the ccRCC grades and Tumor stages (T stages) of ccRCC patients." (PMID 36728187, 2023). "Based on the SCNA module of the TIMER2.0 database, we explored the potential link between the copy number alterations of RNASET2 and infiltration levels of TILs in the tumor microenvironment of ccRCC." (PMID 37679715, 2023). "Secretion of RNASET2 in the tumor environment defines its role as a potential ‘alarmin’ galvanizing an innate immune response and recruitment of M1-polarized macrophages." (PMID 36466822, 2022). "Tumor cell secretion of RNASET2 in the extracellular milieu triggers cellular migration and activation of innate immune cells and extensive cytoskeletal-actin remodeling." (PMID 36466822, 2022). "Of note, the few tumor-producing RNASET2-transfected clones were later shown to have partially or completely lost expression of this gene, thus validating the notion of RNASET2 as a dosage-sensitive, class II TSG." (PMID 36012339, 2022). "Of note, these functional data are totally in keeping with those previously reported in RNASET2-KD OVCAR3 cells in suggesting a role for RNASET2 in tumor suppression in vitro." (PMID 36012339, 2022). "The clinicopathologic feature analysis results demonstrated that the expression of RNASET2 protein was significantly positively correlated with tumor cell differentiation (p < 0.001)." (PMID 32528897, 2020). "Taken together, these data provide a clear support for RNASET2 secretion as a crucial step for in vivo tumor suppression." (PMID 25797262, 2015). "Here, we present data indicating that RNASET2-knockdown actually affects several in vitro cancer-related parameters that are compatible with a cell-autonomous role for RNASET2 in tumor growth control under stress conditions." (PMID 25797262, 2015). "Altogether, these observations suggest a highly pleiotropic role for RNASET2 in tumor suppression, whereby several independent cellular parameters related to cancer growth are affected by changes in the expression levels on this protein." (PMID 25797262, 2015). "Our analysis revealed a significant decrease in RNASET2 levels within HCC tumor tissues." (PMID 39903758, 2025). "Although our data are derived from overexpression models, they also suggest a possible translational application, where recombinant RNASET2 could be explored as a therapeutic agent to modulate the tumor microenvironment in selected PCa subsets." (PMID 40389981, 2025). "RNASET2 overexpression in vivo induced a shift toward M1-like macrophage polarization pattern, while decreasing the M2-like polarization in mice challenged with 22Rv1 cells, indicating a potential tumor-suppressive role in PCa." (PMID 40389981, 2025). "Furthermore, a comparative analysis of three distinct single-cell RNA-seq data sets revealed that RNASET2 is predominantly expressed by tumor microenvironment cells, particularly immune cells, fibroblast, and epithelial cells." (PMID 40389981, 2025). "Moreover, silencing of RNASET2 in human macrophages down-regulates M1 markers, while upregulating M2 markers, supporting its tumor suppressive role within the TME." (PMID 40389981, 2025).
tumor (continued). "Thus, a solid body of evidence gathered over the last two decades points to RNASET2 as a highly pleiotropic tumor suppressor gene, endowed with the ability to counteract cancer cell growth by several independent mechanisms." (PMID 40389981, 2025). "Considering a recent report pointing at RNASET2 as a candidate biomarker for low vs. high-grade PCa, we chose two cell lines (PC-3 and 22Rv1) representing poorly and highly aggressive forms of this tumor type, respectively, to investigate putative differences in their response to RNASET2 modulation." (PMID 40389981, 2025). "We next investigated whether RNASET2 overexpression affected additional hallmarks of tumor progression, specifically cell adhesion and migration." (PMID 40389981, 2025). "Additionally, IHC assays demonstrated that RNASET2 expression was lower in HCC tumor tissues compared to adjacent non‐tumor tissues, but MET expression was found to be elevated in the tumor tissues." (PMID 39903758, 2025). "Bioinformatics analysis of The Cancer Genome Atlas (TCGA) database indicates that the role of RNASET2 in tumor cells may be cancer-type-dependent and location-specific." (PMID 38576019, 2024). "For instance, human RNASET2 possesses antitumorigenic activity through regulating macrophage polarization in the tumor microenvironment and its inhibition of actin binding activity which suppresses tumor invasion and malignancy." (PMID 37993934, 2023). "It suggested that RNASET2 may instead have different biological effects that are either tumor type‐dependent or related to their stage of progression." (PMID 36728187, 2023). "Then, we determined whether there is a correlation between the RNASET2 protein expression level and several key factors relevant to the patient's health status, including age, gender, tumor size, tumor grades, and clinical tumor node metastasis (cTNM) stages." (PMID 36728187, 2023). "Also, evidence suggests that recombinant human RNASET2 glycoprotein possesses anti-tumor and anti-angiogenic properties in both in vivo and in vitro assays." (PMID 37679715, 2023). "The tumor suppressive activities of RNASET2 have been reported in different tumors." (PMID 36012339, 2022). "Interestingly, by investigating the polarization state of tumor-infiltrating macrophages in RNASET2-expressing tumors, most of the infiltrating macrophages were found to belong to the M1 class, which has long been known to play a strong antitumor role role." (PMID 36012339, 2022). "According to this new model, the recruitment of innate immune cells, belonging to the macrophage lineage, could be envisaged as a key process in RNASET2-mediated tumor suppression in vivo." (PMID 36012339, 2022). "RNASET2 (Ribonuclease T2) functions as a tumor suppressor in preventing ovarian tumorigenesis." (PMID 33767133, 2021). "It is described that inactivation through mutation or by denaturation of human RNASET2 does not suppress its antitumor activity, indicating that this protein also has a catalytic-independent role in tumor suppression." (PMID 33435285, 2021). "RNASET2 upregulation, together with the inhibition of phAKT, phmTOR, and Mcl-1 might be part of an “editing” process that leads to the elimination of pro-tumor immature DCs." (PMID 34299186, 2021). "Human RNASET2 has been described as a tumor-antagonizing gene and as a putative stress-sensor." (PMID 32295832, 2020). "Clinicopathologic features and survival analysis demonstrated that RNASET2 protein was significantly correlated with tumor cell differentiation, Lauren's classification, and TM4SF1 protein expression, but not correlated with lymph nodal metastasis and patient's prognosis." (PMID 32528897, 2020). "Besides the anti-tumorigenic activity, RNASET2 suppressed tumor cell motility and aggressiveness by binding cell actin and altering the cytoskeleton network structure." (PMID 32528897, 2020).
tumor (continued). "A role for human RNASET2 in establishing a correlation between tumor initiation/progression and modulation of the immune system was also inferred following the recent finding that the oncogenic virus HTLV-1 tax gene product drives a strong down-regulation of RNASET2 gene expression." (PMID 25797262, 2015). "In this report, we clearly demonstrate that the RNase activity is not necessary for the antitumorigenic and antiangiogenic effects of RNASET2, implying that RNases can simultaneously influence several functions in the tumor cells, unrelated to their RNASE activity." (PMID 25426551, 2014). "Ribonuclease-2 (RNASET2), an extracellular RNase expressed in the OC stroma, was shown to mediate recruitment of macrophages to the tumor microenvironment and its silencing enhanced tumor growth of OVCAR-3 cells in vivo." (PMID 24860785, 2014). "We next asked whether some of these genes could have any relevance in RNASET2-mediated tumor suppression in vivo." (PMID 21646684, 2011). "As for the third gene whose change in expression level was confirmed in vivo (LMCD1), its direct involvement in RNASET2-mediated tumor suppression is rather speculative." (PMID 21646684, 2011). "However, although we elucidated the signaling pathway through which changes in RNASET2 expression levels modulate ccRCC oncogenesis in vitro, some important experiments in vivo, such as tumor xenograft in nude mice, are still needed to clarify how such changes affect ccRCC oncogenesis." (PMID 36728187, 2023). "Moreover, three cancer-related genes whose expression was altered in vitro by RNASET2 modulation (LMCD1, RELB and DSE) showed the same pattern when assessed in vivo, thus pointing at these genes as bona fide effector genes for RNASET2-mediated tumor suppression." (PMID 36012339, 2022). "Moreover, pretreatment of the mice with a macrophage-depleting agent (clodronate liposomes) significantly impaired the ability of RNASET2 to suppress tumor growth in vivo, thus suggesting that host macrophages played a key role in RNASET2-mediated tumor suppression." (PMID 36012339, 2022). "Besides its antitumorigenic role by the recruitment to the tumor mass of immune cells from the monocyte/macrophage lineage, RNASET2 is induced by cellular stress and involved in actin cytoskeleton remodeling affecting cell interactions with the extracellular matrix (ECM)." (PMID 30813308, 2019). "Indeed, our present in vitro data indicate that RNASET2 could act as a sensor able to thwart protumorigenic signals exerted by the interactions between tumor cells and ECM." (PMID 30813308, 2019). "Our previous studies supported that in addition to IRF1, TMEM230, RNASET2, and SDC2 have tumor promoting and inhibiting functions." (PMID 40862725, 2025). "Like IFNs, RNASET2, syndecans, and TMEM230 appear to have both pro- and anti-cancer activities, depending on their levels of expression in different cells of the tumor mass." (PMID 40862725, 2025). "Since ccRCC is the main type of tumor in kidney malignancy, we analyzed using TCGA datasets at GEPIA2 and found that RNASET2 gene expression was significantly higher in ccRCC tissues compared with that in other cancers." (PMID 36728187, 2023). "Taken together, these results highlight how hypoxia- dependent and -independent pathways shape RNASET2 expression in DCs, with new perspectives on its implication for TME and, therefore, in anti-tumor immunity." (PMID 34299186, 2021). "Our study, albeit preliminary, opens new perspectives on the role of RNASET2 in a hypoxic microenvironment as TME and, therefore, in anti-tumor immunity." (PMID 34299186, 2021). "Our study, albeit preliminary, opens new perspectives on the role of RNASET2 in a hypoxic microenvironment as TME and so in anti-tumor immunity." (PMID 34299186, 2021). "In contrast, no change in tumor growth was observed in mice injected with RNASET2-overexpressing PC-3 cells, confirming their resistance to RNASET2-mediated suppression." (PMID 40389981, 2025).
tumor (continued). "Further cell viability assay and colony formation assay demonstrated that RNASET2 was indeed not a tumor suppressor gene in AGS." (PMID 32528897, 2020). "Such non-cell autonomous role as a tumor suppressor was also suggested by the observed RNASET2-mediated chemotactic properties toward cells of the monocyte/macrophage lineage." (PMID 25797262, 2015). "In summary, the present findings demonstrate that trT2-50, a non-glycosylated version of the full-length human RNASET2 devoid of ribonuclease activity, still maintains its actin-binding activity and strongly inhibits tumor progression and angiogenesis." (PMID 25426551, 2014). "Of note, the fact that intracellular RNASET2 may control cell proliferation/survival is not restricted to tumor cells." (PMID 34299186, 2021). "Furthermore, RNASET2 displays a non-cell autonomous oncosuppressive role altering the balance between the pro- and anti-tumor roles of the innate immune system through acting as an alarmin-like macrophage-mediated tumor suppressor gene." (PMID 33435285, 2021). "In this study, RNASET2 expression appears to negatively affect the interaction of tumor cells with ECM proteins in vitro in two independent EOC cellular models characterized by a marked difference in their aggressiveness, pointing to a widespread oncosuppressive role for RNASET2 in EOC." (PMID 30813308, 2019). "RNASET2 was differentially expressed in the UNC4 and EPI2 cell clusters but the number of cells was too few to identify in these clusters molecular pathways differentially regulated between HER2+ tumor and non-malignant breast." (PMID 40862725, 2025).